H2BC13 (H2B clustered histone 13)
Description:
Core component of nucleosome. Nucleosomes wrap and compact DNA into chromatin, limiting DNA accessibility to the cellular machineries which require DNA as a template. Histones thereby play a central role in transcription regulation, DNA repair, DNA replication and chromosomal stability. DNA accessibility is regulated via a complex set of post-translational modifications of histones, also called histone code, and nucleosome remodeling.
Synonyms: H2B/c; H2BFC; HIST1H2BL; dJ97D16.4
Tractability: PROTAC: UniProt records ubiquitination sites on it; ubiquitination databases record sites on it.
Gene: Protein-coding gene on chromosome 6 (27,807,479 to 27,807,929, reverse strand). Ensembl gene ENSG00000185130.
Subcellular location: Nucleus; Chromosome
Subcellular location (Human Protein Atlas): Nucleoplasm; Cytosol
Pathways (Reactome):
Gene expression (Transcription): B-WICH complex positively regulates rRNA expression; DNA methylation; ERCC6 (CSB) and EHMT2 (G9a) positively regulate rRNA expression; MLL4 and MLL3 complexes regulate expression of PPARG target genes in adipogenesis and hepatic steatosis; NoRC negatively regulates rRNA expression; PRC2 methylates histones and DNA; RNA Polymerase I Promoter Escape; RNA Polymerase I Promoter Opening; RUNX1 regulates genes involved in megakaryocyte differentiation and platelet function; RUNX1 regulates transcription of genes involved in differentiation of HSCs; Regulation of endogenous retroelements by KRAB-ZFP proteins; Regulation of endogenous retroelements by Piwi-interacting RNAs (piRNAs); Regulation of endogenous retroelements by the Human Silencing Hub (HUSH) complex; SIRT1 negatively regulates rRNA expression; Transcriptional regulation by small RNAs
Chromatin organization: CHD1 and CHD2 subfamily; CHD6, CHD7, CHD8, CHD9 subfamily; ChAHP complex assembly; HATs acetylate histones; HDACs deacetylate histones; Interaction of NuRD complexes with transcription factors; NuRD complex assembly
DNA Repair: Cleavage of the damaged purine; Cleavage of the damaged pyrimidine; Nonhomologous End-Joining (NHEJ); Processing of DNA double-strand break ends; Recognition and association of DNA glycosylase with site containing an affected purine; Recognition and association of DNA glycosylase with site containing an affected pyrimidine; Recruitment and ATM-mediated phosphorylation of repair and signaling proteins at DNA double strand breaks
Cell Cycle: Condensation of Prophase Chromosomes; Deposition of new CENPA-containing nucleosomes at the centromere; G2/M DNA damage checkpoint; Inhibition of DNA recombination at telomere; Packaging Of Telomere Ends
Developmental Biology: Activation of anterior HOX genes in hindbrain development during early embryogenesis; Chromatin modifications during the maternal to zygotic transition (MZT); Replacement of protamines by nucleosomes in the male pronucleus; Transcriptional regulation of granulopoiesis
Disease: Defective pyroptosis; Dengue Virus-Host Interactions
and 18 more pathways
Gene Ontology:
Molecular function: protein binding; DNA binding; structural constituent of chromatin; protein heterodimerization activity
Biological process: antibacterial humoral response; antimicrobial humoral immune response mediated by antimicrobial peptide; chromatin organization; innate immune response in mucosa; nucleosome assembly
Cellular component: extracellular exosome; nucleus; nucleoplasm; nucleosome; chromosome
Genetic constraint (gnomAD): Loss-of-function variants: 12 observed, 6.49 expected, observed/expected ratio (o/e) 1.85, 90% interval 1.08 to 1.96. That is too few expected variants to judge how well the gene tolerates losing a copy. Missense variants: 164 observed, 175.78 expected, observed/expected ratio (o/e) 0.93, 90% interval 0.82 to 1.06. Synonymous variants: 109 observed, 75.92 expected, observed/expected ratio (o/e) 1.44, 90% interval 1.23 to 1.68.
Homologues: Orthologues: mouse H2bc11 (99% identical), mouse H2bc13 (99% identical), mouse H2bc15 (99% identical), mouse H2bc7 (99% identical), chimpanzee H2BC13 (98% identical), macaque H2BC9 (98% identical), mouse H2bc12 (98% identical), mouse H2bc23 (98% identical), mouse H2bc24 (98% identical). Paralogues in human: H2BC10 (98% identical), H2BC4 (98% identical), H2BC6 (98% identical), H2BC7 (98% identical), H2BC8 (98% identical), H2BC12 (98% identical), H2BC15 (98% identical), H2BC21 (98% identical), H2BC5 (98% identical), H2BC9 (98% identical), H2BC11 (97% identical), H2BC17 (97% identical), and 9 more.
Diseases named in the same sentence as H2BC13 in open-access papers:
H2BC13 is named in the same sentence as 10 diseases in open-access papers, as found by Europe PMC text mining. Sharing a sentence is not in itself a finding about the gene and the disease.
H2BC13 shares sentences with these, for which no sentence is quoted: systemic lupus erythematosus (4 papers); cancer (2); autoimmune disease (1); bipolar disorder (1); breast tumours (1); cervical cancer (1); endometrial cancer (1); immune disease (1); melanoma (1); pancreatic cancer (1).